FOXP3 (forkhead box P3)
Diseases named in the same sentence as FOXP3 in open-access papers (continued):
Sharing a sentence is not in itself a finding about the gene and the disease.
tumor (continued). "Increased suppressive activity of MDSCs is associated with increased level of CD4+/CD25+/FoxP3+ Treg cells in the tumor environment." (PMID 34070449, 2021). "Analysis of FoxP3 showed statistically significant association of the number of FoxP3+ Treg with histotype of the tumor." (PMID 33466316, 2021). "On the other hand, the presence of CD3+, CD8+, or FoxP3+ lymphocyte infiltration in the tumor invasive margins were associated with markers of good prognosis." (PMID 34440038, 2021). "On the other hand, increased tumor infiltration by FoxP3-expressing T lymphocytes has been associated with reduced overall survival of patients with different types of cancer, including breast, lung, and cervical cancers." (PMID 34440038, 2021). "Treg cells in severe COVD-19 patients present a striking Treg phenotype, which associates an up-regulation of FoxP3 expression with a distinctive transcriptional signature that bears much similarity to tumor Tregs." (PMID 34433692, 2021). "We also found that the high accumulation of FoxP3+ T lymphocytes in the tumor margins was associated with TNM stages I-II, normal CEA levels, and, more importantly, with the non-invasion of lymph nodes." (PMID 34440038, 2021). "On the other hand, the infiltration of CD3+, CD8+, or FoxP3+ lymphocytes in the tumor invasive margins were associated with the pathogenesis of CRC, but only FoxP3+ T lymphocyte infiltrations were inclined to indicate favorable prognosis." (PMID 34440038, 2021). "The ablation in the expression of Foxp3 can cause prostate hyperplasia in mice, indicating that Foxp3 can act as a tumor suppressor during the initiation of tumors." (PMID 34670484, 2021). "Our study supports the associations of tumor FOXP3/CD3 ratios, IL17A and IL2 with outcome in the rituximab era." (PMID 33648463, 2021). "Although cytotoxic tumor-infiltrating lymphocytes (TILs) are often associated with favorable clinical outcomes, the relationship between FOXP3+ TIL and the prognosis is less clear." (PMID 34712661, 2021). "Using scRNASeq of TILs from LUAD, we found that LAIR2 was predominantly expressed by tumor-associated CD4+ FoxP3+ Treg cells, the presence of which have widely been associated with negative outcomes in a variety of cancers." (PMID 35008369, 2021). "This was associated with significant reductions in tumor associated FOXP3+ cellular infiltration and CD163+ M2-type macrophage infiltration." (PMID 34715561, 2021). "Increased infiltration of CD3+CD8+ and CD3+Foxp3+ tumor-infiltrating lymphocytes (TILs) are associated with better prognosis in HNSCC." (PMID 33477635, 2021). "Differentiated, functional T-reg cells have cell surface receptors CD4 and FoxP3 among others and are associated with suppressed anti-tumor immunity." (PMID 33615011, 2021). "Overall, our data show that the presence of CD3+, CD8+, or FoxP3+T lymphocytes in the tumor invasive margin are associated with the pathogenesis of CRC." (PMID 34440038, 2021). "The findings of set 1 indicate that the ratio of CD8+ TNFR2+ PD-1+ TILs over CD4+ TNFR2+ FOXP3+ TILs was significantly higher in the chemotherapy-treated mice compared to the vehicle-treated mice, and was significantly associated with reduced tumor volumes." (PMID 34201054, 2021). "B7-H3 expression was strongly associated with tumor-infiltrating FoxP3+ Tregs, and patients with the highest expression of B7-H3+FoxP3+ Tregs had the poorest survival of all groups." (PMID 34141625, 2021). "A trend of increased CD8+ cytotoxic T lymphocytes (CTLs) and decreased CD163+ tumor-associated macrophages (TAMs) and Foxp3+ regulatory T cells (Tregs) in the pCR group was revealed by IMC." (PMID 34733785, 2021). "In a group of 110 NSCLC specimens, FoxP3 expression in tumor-infiltrating T-cells was associated with male gender, regional lymph node involvement, advanced clinical stage, and poor overall survival." (PMID 34141625, 2021).
tumor (continued). "MicroCellClust identifies a cluster of 23 cells originating from the tumor, characterized by the expression of Treg associated genes such as FOXP3 and IL2RA." (PMID 33830183, 2021). "Within the tumour compartment, those tumours with increased levels of PD-L1, FOXP3 and GITR expression were associated with longer OS." (PMID 35083152, 2021). "For example, interleukin‐2‐mediated STAT3 activity expands tumour‐associated regulatory T cells and enhances Foxp3 expression in CD4+ T cells." (PMID 34449972, 2021). "PD-1 and PD-L1 expression associates with CD4+, CD8+ and FOXP3+ tumor infiltrating lymphocytes related to poor survival in CCRCC." (PMID 33562338, 2021). "Tregs, which are abundant in the tumor stroma is a specific subgroup of CD4+ T cells expressing the transcription factor Foxp3, CD25 and cytotoxic T-lymphocyte-associated antigen-4 (CTLA-4)." (PMID 34062992, 2021). "Tumor localization was associated with the presence of FOXP3+ cells (p = 0.029), low numbers of FOXP3+ cells being more common in tumors of the antrum/pylorus." (PMID 32954467, 2021). "Increased IL-10+ B cell numbers in ME can also be associated by increased numbers of Foxp3+ Tregs, which are independently associated with tumour progression or reduced patient survival." (PMID 34298847, 2021). "A comparison of frequencies of FoxP3+ cells within the CD4+ T cell subset for tumor associated cells and blood (PBMC) for each patient revealed a significantly higher frequency of FoxP3+ cells in tumor vs. blood for each patient (p = 0.001)." (PMID 34926643, 2021). "Treg cells (FOXP3+Tregs) along with myeloid-derived suppressor cells (MDSCs) and tumor-associated macrophages (TAMs) type 2, perform immunosuppressive functions by their high level accumulations in TME." (PMID 34055618, 2021). "It has been reported that high density of intratumoral CD8+ and FoxP3+ tumor-infiltrating lymphocytes were associated with good prognosis." (PMID 34900669, 2021). "The number of TILs (CD45+, CD3+, CD4+, CD8+, and FOXP3+) and tumor‐associated macrophages (CD163+) was counted using immunohistochemistry on tissue microarray slides." (PMID 34076969, 2021). "In some studies, the density of FOXP3+ tumor-infiltrating cells correlated positively with a prolonged patient survival, and accordingly, stage II CRC patients with poor CD3+ and FOXP3+ infiltration presented a higher risk of tumor progression." (PMID 34072037, 2021). "The numbers of CD8 + and FOXP3 + were also associated with tumor size, histologic grade, PR expression, and mitotic index." (PMID 34117905, 2021). "A portion of CD8+ CD28null cells from patients with glioblastoma express Foxp3 and are associated with a tolerogenic phenotype of tumor-infiltrating APCs that express ILT2, ILT3, and ILT4." (PMID 34680058, 2021). "In conclusion, our results indicate that only the presence of high infiltrates of CD3+, CD8+, and FoxP3+ T lymphocytes in the tumor invasive margins are associated with good prognostic indicators and potentially limit the aggressiveness and spread of CRC." (PMID 34440038, 2021). "In contrast to M1 macrophages, CTLs and NK cells, immunosuppressive CD4+FoxP3+Tregulatory cells (Tregs), tumor-associated M2 macrophages, N2 neutrophils and myeloid-derived suppressor cells (MDSCs) promote tumor growth and progression." (PMID 34830312, 2021). "In the present study, IDO expression in tumor cells was positively associated with high amounts of FoxP3+ Tregs." (PMID 34051744, 2021). "High levels of TGFβ1 were positively associated with PD-L1, CD206, and FoxP3 levels in tumor tissues, but inversely with that of CD8, CD56, and CD86." (PMID 34095135, 2021). "Further studies revealed that the Fusobacterium DNA load in MSI-high colorectal cancer tumors was inversely associated with tumor-infiltrating FoxP3+ T cell density and positively correlated with the ratio of M2-like TAMs to TAMs." (PMID 34656142, 2021).
tumor (continued). "FOXP3 expression and the CD8 to FOXP3 ratio in the tumor stroma as well as the loss of PTEN expression in tumor cells are prognostic factors in non-metastatic TNBC." (PMID 34362334, 2021). "We tested CD45+, CD3+, CD4+, CD8+, and Foxp3+ immune markers in both the tumor core area and tumor-associated stroma." (PMID 33580130, 2021). "Conversely, tumor-associated FoxP3+CD4+ T cells (regulatory T cells) that induce immunosuppression and promote tumor progression and metastasis were concomitantly reduced." (PMID 33491667, 2021). "Co-localization of mast cells and FOXP3+ Treg cells was observed in selective areas of the tumor sections presumably causing localized pockets of resistance." (PMID 33436641, 2021). "In new work by Martinez-Usatorre and others, depletion of TAMs was associated with Treg down-regulation (along with FOXP3 down-regulation) as well as restoration of tumor inhibition and regression under PD-1 blockade in the models." (PMID 34715561, 2021). "Substantial reductions in suppressive cytokines, including CCL2, CCL17, CCL22 and IL-10, were also noted and were associated with reduced CD4+ CD25+ Foxp3+ Treg recruitment in the tumour." (PMID 33513866, 2021). "A similar result was noted for comparison of FoxP3+ cell frequencies within the CD4-CD8- T cell subset with higher frequencies detected in tumor associated cells compared to blood for each patient (p = 0.001)." (PMID 34926643, 2021). "Their high frequency among CD4+ T cells within tumor-infiltrating lymphocytes (TILs) or a high ratio of FOXP3+ Tregs to CD8+ T cells is associated with a poor prognosis in the majority of solid tumors (for review." (PMID 33924428, 2021). "Hierarchical clustering of patients showed four tumor type-independent immune signatures, where infiltration of FOXP3+ cells and M1-like macrophages associated with favorable prognosis." (PMID 34799669, 2021). "Together, these results show that high infiltrations of CD3+, CD8+, or FoxP3+T lymphocytes in the tumor margins are associated with good prognostic indicators." (PMID 34440038, 2021). "While tumour-associated LECs support the migration of tumour cells, they can enhance Foxp3-regulatory T cell functions and suppress responses of effector T cells, as demonstrated from the gain of a phenotype similar to that of lymphatic node LECs in mice." (PMID 32929219, 2021). "We further identified expression of CTLA-4 and FoxP3 in both interstitial and tumor cells, with a positive association between interstitial expression of CTLA-4 and FoxP3, which was also associated with lower serum CTLA-4 levels." (PMID 32123292, 2020). "Because they can inhibit anti-tumor immunity, high numbers of tumor-infiltrating FoxP3+ T-cells are associated with poor prognosis." (PMID 32785290, 2020). "Other studies found that high levels of FOXP3+ TILs predicted poor prognosis in luminal tumours, with an association of poor response to neoadjuvant letrozole in post treatment biopsies." (PMID 32825588, 2020). "CD276 expression is also associated with tumor-infiltrating FOXP3 + regulatory T cells which inhibit effector T cells and is important for immune evasion and tumorigenesis in prostate cancer." (PMID 33033253, 2020). "CA9 expression by cancer cells is associated significantly with FOXP3+ regulatory T-cell abundance in the tumour stroma of NSCLC." (PMID 32066909, 2020). "Addition of anti‐CTLA‐4 antibodies to ILP‐TNF/Mel/SM led to a significant increase of T helper cells and also caused a reduction of intra‐tumoural CD3+CD4+Foxp3+ regulatory T cells." (PMID 32419365, 2020). "Cancer-associated fibroblasts (CAFs) promote tumor immunosuppression by releasing IL-6, which increases the number of FoxP3+ Treg cells." (PMID 33234169, 2020). "The tumour suppressor miR146a, (and its relative miR-146b) is up-regulated by FOXP3 and targets IRAK1 and TRAF6 causing NF-kB inactivation in the Luminal A subtype." (PMID 32188472, 2020).
tumor (continued). "It seemed that both FOXP3 and CD4 were associated with tumor progression, but FOXP3 was a stronger indicator." (PMID 32222891, 2020). "It is concluded that CA9 is a marker strongly associated with FOXP3+ regulatory T-cell abundance in the tumour environment of NSCLC." (PMID 32066909, 2020). "In this work we evidence that a Foxp3 variant known to affect regulatory T cell functions acts as an hypomorph in a tumor context and enhances the effectiveness of anti‐CTLA4 immunotherapy." (PMID 31729760, 2020). "The number of FOXP3+ positive T cells seems to be associated with tumor aggressiveness, since BLBCs have the highest FOXP3+/CD8+ T lymphocytes ratio and luminal A has the lowest." (PMID 33143050, 2020). "In contrast, FOXP3 + cells were only associated within TN tumours showing high SLC expression (p = 0.02)." (PMID 31819174, 2020). "To confirm our analytical results, we first selected two representative tumor samples from the high- and low-risk groups and stained α-SMA and Foxp3 in the two tumor sample slices using the immunofluorescent assay method." (PMID 33392181, 2020). "PitNETs with more CD4+ T cells had higher microvessel area, while tumours with more FOXP3+ cells were associated with lower microvessel density." (PMID 32946040, 2020). "In breast cancer, RANKL is also produced by Foxp3-expressing Tregs and tumor-associated macrophages (TAMs) that can affect tumor growth, tumor cell dissemination, and metastasis." (PMID 32850393, 2020). "Studies to date generally agree that CD8+ cytotoxic T lymphocytes (CTLs) and CD4+ Th1 cells are involved in effective anti-tumor immunity while FOXP3+ regulatory T cells are associated with suppression of anti-tumor immunity." (PMID 32216826, 2020). "A correlation between the grade of tumor budding and the immune system invasion has been reported, with high grade of tumor budding being associated with FOXP3+ regulatory T cells invasion and worse prognosis." (PMID 32206189, 2020). "This is mediated by reduced T-box expressed in T cells (T-bet) and increased forkhead box protein P3 FoxP3 expression in tumor-associated CD4+ T cells." (PMID 33086598, 2020). "In the CD8-high group, FAP intensity was significantly associated with a higher total tumor density of FoxP3-positive immune cells and a higher ratio of epithelial-to-stromal density of CD8a T cells." (PMID 33153037, 2020). "Consistent with FACS data, the deficiency of Bcl6 resulted in reduced expression of Foxp3 in Treg cells in tumor model." (PMID 32477338, 2020). "Mice with restricted deletion of TRAF6 in Tregs were resistant to implanted tumours and displayed enhanced antitumour immunity because Foxp3 underwent K63-linked ubiquitination at lysine 262 as mediated by TRAF6." (PMID 32680511, 2020). "Tumor-associated macrophages (TAMs) and forkhead box protein P3 (FoxP3)+ Treg cells are commonly associated with a poor clinical outcome." (PMID 33234169, 2020). "In contrast, worse clinical performance, increased enhancing tumor volume, and low FoxP3 immune response were associated with a shorter OS in male patients." (PMID 32560244, 2020). "An association between a high number of tumor‐associated FOXP3+ T cells and improved survival was also observed in this study." (PMID 32377339, 2020). "Lastly, FOXP3+ T-cells at the tumor center were associated with improved prognosis for cancer-specific survival (HR = 0.65, p < 0.01) and overall survival (HR = 0.70, p < 0.01)." (PMID 32099066, 2020). "This suppressive environment appears to be particularly important for differentiating outcome in luminal A tumours, in which both FOXP3+ and PDL1+ were associated with poor outcome." (PMID 32203210, 2020). "In tumor‐associated Treg cells, Hat1 was found to physically associate with the transcription factor FoxP3." (PMID 31290578, 2019).
tumor (continued). "In various reports, a high frequency of CD8+ tumor-infiltrating lymphocytes or a low frequency of MDSCs or FOXP3+ Tregs in tumors was associated with longer survival in the targeted tumor types." (PMID 31208461, 2019). "Increased FoxP3 expression was a marker of the presence of Tregs within the tumor, and this was associated with both a decrease in progression-free and overall survival." (PMID 31091744, 2019). "A recent meta-analysis listing 76 studies and more than 15,000 patients showed that FoxP3+ Treg infiltration in tumor is associated with patient’s survival." (PMID 30781400, 2019). "The primary function of FOXP3+ Tregs is to eliminate self-reactive lymphocytes, and most tumor-associated antigens are regarded as self." (PMID 31852159, 2019). "S1P1 expression in tumor specimens exhibits a significant positive association with the tumor-infiltrated Foxp3+ Treg density, and both of these features are associated with poor OS in BC patients." (PMID 30718502, 2019). "Compared with the non-mutated ones, the microenvironment of BRAF mutated tumors is characterized by a twice as high density of FOXP3+ Regulatory T cells (Tregs), which, by inhibiting the anti-tumor immune response, are associated with a poor prognosis." (PMID 31762942, 2019). "In a study of lung adenocarcinoma, EMT markers were associated with enhanced tumor infiltration of CD4+Foxp3+ Tregs and upregulation of inhibitory immune checkpoint molecules such as programmed cell death (PD)-ligand (L) 1, PD-L2, TIM-3, B7-H3, and CTLA-4." (PMID 31096701, 2019). "An association between tumor infiltrating FOXP3+ Tregs and a dismal prognosis has been shown in several cancers." (PMID 31068935, 2019). "In human tumors, infiltration of tumor sites with Foxp3 Treg cells can be associated with a less favorable prognosis." (PMID 30800128, 2019). "In tumours with effective Tregs, high FoxP3+ expression is associated with poor prognosis, whilst in tumours with non-Tregs, this was not the case." (PMID 30232514, 2019). "CCL20 expression was positively associated with FOXP3 expression in tumor tissues as analyzed by immunohistochemistry." (PMID 31395078, 2019). "Regulatory T cells (Tregs), expressing FoxP3, are associated with poor survival as they can suppress tumor-specific T cell immune responses." (PMID 31443339, 2019). "Our data also revealed that the upregulation of the regulatory T-cells (Tregs) associated marker, Foxp3, at the tumor stromal interface of PDAC derived from the PKTP mice, compared with that of the PKP model." (PMID 31109321, 2019). "High density of Foxp3+ cells in tumor tissues was associated with improved survival in CRC patients." (PMID 31048714, 2019). "MDSCs inhibit anti-cancer immune responses by releasing cytokines (IL-1 and TGF-β), ROS, and reactive nitrogen species (RNS) that condition the tumor microenvironment and by stimulating Foxp3+ Treg cells and M2 tumor-associated macrophages (TAM)." (PMID 31412566, 2019). "Foxp3 + staining unveiled a significant (P < 0.0001) decline in the amount of tumor-associated immunosuppressive regulatory T-cells compared to controls, at both day 3 and 6 after 90Y-NM600 injection." (PMID 30820474, 2019). "It was also found that the number and function of CD4+/CD25+/FoxP3+ Tregs in the lymph nodes, spleen, and tumor tissue are reduced in the B-cell-deficient mouse model, resulting in significant inhibition of tumor development." (PMID 31662750, 2019). "Nrp-1 deficiency on murine FoxP3+ CD4+ Treg cells has been reported to delay tumour growth correlated with enhanced activation of tumour-infiltrating CD8+ T cells." (PMID 31350404, 2019). "Studies have shown that forkhead/winged helix transcription factor P3 (FOXP3)+ tumor infiltrating lymphocytes (TILs) are intimately associated with invasion and survival of many invasive tumors." (PMID 31852159, 2019).